SRRM5 (serine/arginine repetitive matrix 5)
Tractability: PROTAC: ubiquitination databases record sites on it.
Gene: Protein-coding gene on chromosome 19 (43,596,617 to 43,614,498, forward strand). Ensembl gene ENSG00000226763.
Subcellular location (Human Protein Atlas): Vesicles; Centrosome
Genetic constraint (gnomAD): Loss-of-function variants: 2 observed, 2.09 expected, observed/expected ratio (o/e) 0.95, 90% interval 0.35 to 1.87. That is too few expected variants to judge how well the gene tolerates losing a copy. Missense variants: 874 observed, 942.93 expected, observed/expected ratio (o/e) 0.93, 90% interval 0.88 to 0.98. Synonymous variants: 275 observed, 329.91 expected, observed/expected ratio (o/e) 0.83, 90% interval 0.75 to 0.92.
Homologues: Orthologues: chimpanzee SRRM5 (94% identical), pig SRRM5 (56% identical), dog SRRM5 (53% identical), mouse Gm50092 (39% identical), rat AABR07002689.1 (37% identical).